MIR3074 (microRNA 3074)
Synonyms: hsa-mir-3074; mir-3074
Gene: MicroRNA gene on chromosome 9 (95,086,014 to 95,086,094, reverse strand). Ensembl gene ENSG00000207617.
Gene Ontology:
Biological process: miRNA-mediated post-transcriptional gene silencing
Cellular component: RISC complex
Homologues: Orthologues: chimpanzee MIR3074 (100% identical), macaque MIR3074 (98% identical), pig ssc-mir-24-2 (98% identical), zebrafish dre-mir-24-4 (59% identical), tropical clawed frog xtr-mir-24a (54% identical), mouse Mir24-1 (53% identical). Paralogues in human: MIR24-1 (54% identical), MIR24-2 (52% identical).